PDXDC2P (pyridoxal dependent decarboxylase domain containing 2, pseudogene)
Synonyms: PDXDC2; DKFZp761H1120
Gene: Transcribed unprocessed pseudogene on chromosome 16 (70,010,751 to 70,065,776, reverse strand). Ensembl gene ENSG00000255185.
Diseases named in the same sentence as PDXDC2P in open-access papers:
PDXDC2P is named in the same sentence as 3 diseases in open-access papers, as found by Europe PMC text mining. Sharing a sentence is not in itself a finding about the gene and the disease. The quoted sentences say what the papers report.
Alzheimer disease (1 paper, 2024). A progressive, neurodegenerative disease characterized by loss of function and death of nerve cells in several areas of the brain leading to loss of cognitive function such as memory and language. "Moreover, the CC2D2B, PDXDC2P, and MBIP genes exhibited strong negative associations, which are also linked to Alzheimer's disease (AD), thus suggesting that healthy diets may help maintain cognition during aging." (PMID 39351424, 2024).
tumor (2 papers, 2019 to 2022). "By interacting with the TCGA RNA-seq data, we found expression levels of H19 and PDXDC2P were significantly changed between tumor and adjacent normal (p-value = 9.39e−8 for H19 and p-value = 0.0083 for PDXDC2P, t-test)." (PMID 36578923, 2022).
PDXDC2P also shares sentences with these, for which no sentence is quoted: thyroid abnormality (1 paper).